H1-7 (H1.7 linker histone)
Description:
Essential for normal spermatogenesis and male fertility. Required for proper cell restructuring and DNA condensation during the elongation phase of spermiogenesis. Involved in the histone-protamine transition of sperm chromatin and the subsequent production of functional sperm. Binds both double-stranded and single-stranded DNA, ATP and protamine-1.
Synonyms: H1FNT; HANP1; H1T2; H1.7
Tractability: No criterion of Open Targets' tractability assessment is met for any kind of drug.
Gene: Protein-coding gene on chromosome 12 (48,328,980 to 48,330,279, forward strand). Ensembl gene ENSG00000187166.
Subcellular location: Nucleus; Chromosome
Subcellular location (Human Protein Atlas): Connecting piece; End piece; Mid piece; Perinuclear theca; Principal piece
Gene Ontology:
Molecular function: protein binding; double-stranded DNA binding; nucleosomal DNA binding
Biological process: chromosome condensation; negative regulation of DNA recombination; sperm DNA condensation; spermatid nucleus elongation
Cellular component: nucleus; chromatin; chromosome
Genetic constraint (gnomAD): Loss-of-function variants: 2 observed, 1.14 expected, observed/expected ratio (o/e) 1.76, 90% interval 0.5 to 1.93. That is too few expected variants to judge how well the gene tolerates losing a copy. Missense variants: 358 observed, 325.66 expected, observed/expected ratio (o/e) 1.1, 90% interval 1.01 to 1.2. Synonymous variants: 162 observed, 143.51 expected, observed/expected ratio (o/e) 1.13, 90% interval 0.99 to 1.29.
Homologues: Orthologues: chimpanzee H1-7 (98% identical), macaque H1-7 (90% identical), pig H1-7 (58% identical), dog H1-7 (56% identical), rat H1f7 (48% identical), mouse H1f7 (48% identical), Caenorhabditis elegans hil-2 (12% identical), Caenorhabditis elegans hil-4 (12% identical), Caenorhabditis elegans hil-6 (12% identical), Caenorhabditis elegans hil-3 (11% identical), Caenorhabditis elegans hil-5 (10% identical). Paralogues in human: H1-4 (23% identical), H1-5 (22% identical), H1-1 (22% identical), H1-3 (21% identical), H1-2 (20% identical), H1-6 (17% identical), H1-8 (15% identical), H1-10 (15% identical), H1-0 (14% identical).
Diseases named in the same sentence as H1-7 in open-access papers:
H1-7 is named in the same sentence as 4 diseases in open-access papers, as found by Europe PMC text mining. Sharing a sentence is not in itself a finding about the gene and the disease. The quoted sentences say what the papers report.
tumor (1 paper, 2020). "Finally, the env-encoded H17 protein of HERV-H was found to induce epithelial-to-mesenchymal transition (EMT) in tumor cells and recruit immunoregulatory suppressor cells, suggesting its contributory role in tumor metastasis and immune escape." (PMID 32759845, 2020).
H1-7 also shares sentences with these, for which no sentence is quoted: Azoospermia (1 paper); Infertility (1); male infertility (1).